TLR4 (toll like receptor 4)
Diseases named in the same sentence as TLR4 in open-access papers (continued):
Sharing a sentence is not in itself a finding about the gene and the disease.
infection (continued). "TLR2 and TLR4 are also suggested to be involved in the production of ROS and NO; however, in the context of Tc infection, TLR2/TLR4 activation appeared to be not sufficient to induce potent ROS/NO response to kill the intracellular parasite." (PMID 29503646, 2018). "The beneficial effects of the donor TLR4 +3725G/G genotype were seen on TRM and death attributable to infections but were not evident with respect to GVHD, suggesting that the donor TLR4 +3725G/G genotype helps prevent fatal infections." (PMID 28484092, 2017). "The absence of either TLR2 or TLR4 significantly reduced the production of TNFα and IL6 after 24 and 48 h of infection." (PMID 28119856, 2016). "W. chondrophila stimulation of CXCL8 secretion in HEK293 cells indicates that TLR2, TLR4, NOD2 and NOD1 receptors are not essential to the innate immune response to infection." (PMID 27002636, 2016). "One possible explanation lied in TLR4 and Dectin‐1 receptors of PBMCs from SAP in the absence of infection were triggered by exogenous macromolecules." (PMID 26893103, 2016). "In another study it was demonstrated that infection of AGS and MKN45 cells with H. pylori resulted in an upregulation of TLR4; however, adding blocking antibodies towards TLR4 failed to inhibit LPS-induced IL-8 secretion." (PMID 25945326, 2015). "Prior to infection (0 h), no expression of IE1–72 was identified, the expression levels of TLR2 and TNF-α were low, and the expression levels of TLR4 and NF-κB were high." (PMID 25435993, 2015). "Similar to what was observed with the mRNA, infection with L. amazonensis reduced the amounts of Fpn1 protein in Fe-NTA-treated wild type, but not TLR4−/− BMDM." (PMID 24497831, 2014). "The mRNA expression of TLR1, TLR2, TLR4 and TLR6 of C. burnetii NM stimulated PBMCs derived from naive and infected goats at day 35 equalled the expression as prior infection (data not shown)." (PMID 25279829, 2014). "Two TLRs, TLR4 and TLR9, were both observed to be expressed differentially upon separate infection with F4ab and F4ac ETEC, while no TLRs expressed differentially after F18ac ETEC infection." (PMID 22823589, 2012). "Here, the infection with P. yoelii 17XL or 17XNL induced the expression of TLR2, but not TLR4 and TLR9, on murine macrophages in the present study." (PMID 22463100, 2012). "Our results show, however, that in the absence of the relevant TLRs, i.e. TLR2 and TLR4, CD4+ T-cells can be sensitized to release IFNγ upon infection with C. pneumoniae." (PMID 22096480, 2011). "An intriguing aspect of our study is that more than 60% of subjects with idiopathic PTL exhibited a significant increase in TLR4 expression in peripheral WBC's, yet did not display clinical indications of infection." (PMID 20964862, 2010). "Since several previous studies have demonstrated the importance of IFN-γ secretion by CD8+ T cells in resistance to infection with T. cruzi, we asked if the frequency of Ag-specific IFN-γ-secreting cells would be altered in the absence of TLR4 expression." (PMID 20442858, 2010). "The results suggest that a host response involving Tlr4 and Myd88 leads to TcpC dependent kidney pathology after CFT073 infection and that hosts lacking Tlr4 or the adaptor are protected from such tissue damage." (PMID 20886104, 2010). "We found an early up-regulation of Ppargc1a and Ppargc1b post-infection (at 6 h) in WT mice, but the expression of both genes was concordantly dysregulated in TLR2−/− mice (no increase at 6 h) and in TLR4−/− mice (amplified at 6 h)." (PMID 20657826, 2010). "Unlike TLR4, the expression of TLR15 was consistently up-regulated with SE challenge (2.44 - fold at 1 h and 3.52 - fold at 4 h post-infection), whereas no significant change was observed in siNF-kB 1 inhibition." (PMID 21637513, 2009). "In line with these in vivo observations, we demonstrated that purified LPS from B. pseudomallei 1026b (the strain also used in the in vivo infection studies) activates HEK293 cells via TLR2, not via TLR4." (PMID 17676990, 2007).
infection (continued). "Moreover, in the absence of NTHi infection, neither TLR2 nor TLR4 inhibitors had an effect on TNFα expression in MDMs." (PMID 40013145, 2025). "The absence of TLR2 and TLR4 results in impaired phagocytosis and reduced levels of TNF-α, IL-6, IL-10, and nitric oxide, which could promote a persistent infection." (PMID 41346968, 2025). "Our findings showed that supplementing the rabbits with TQN significantly (p < 0.05) upregulated the transcription levels of IL-10, TLR-4, DEFB1 and TLR-2 genes comparing with the control non-supplemented rabbits at 96 h post-infection with P. multocida strain." (PMID 38292130, 2023). "Interestingly, a series of mild non-toxic agonists of TLR4 such as MPLA, have been proved to enhance host defense against infection via macrophage phagocytosis, and reduce systemic inflammation." (PMID 35370674, 2022). "Furthermore, we demonstrate the complete TLR4/CD14/MD2 complex to be essential for Ct-LPS uptake by cells, but not for uptake and infection of intact Ct." (PMID 36557742, 2022). "ACE2‐expressing DCs were infected by SARS‐CoV‐2 and both infection and IFN‐β production was blocked by antibodies against ACE2, but not by antibodies against TLR4, suggesting that endosomal TLR4 triggering is not involved in the observed SARS‐CoV‐2‐induced immune activation." (PMID 35099061, 2022). "IL-6 can issue a warning signal in response to both infection and noninfectious tissue damage which may be recognized by TLRs such as TLR2 and TLR4." (PMID 34336088, 2021). "As a result, the expression of TLR2 and TLR10 experienced no obvious alterations during infection, and the expression of TLR5 and TLR6 increased slightly, whereas the expression of TLR4 was downregulated significantly, which were consistent with previous reports." (PMID 33414472, 2021). "In this study we also blocked TLR4 with TLR4-IN-C34 antagonist which did not affect the inflammatory response in MAP-infected macrophages, which confirms that MAP interaction with TLR2 is key during infection." (PMID 33212859, 2020). "As components of Gram-negative bacteria, LPS and CpG-ODN trigger TLR4 and TLR9 at the site of infection, respectively, although the biological effects of these two components may change at different stages of infection." (PMID 32397173, 2020). "In contrast, TLR2, TLR4, and TLR9 play relatively minor roles with minimal or no impact on IFN-γ production by splenocytes, including DC, and the response of the respective KO mice to LVS infection is only modestly compromised." (PMID 32745117, 2020). "Consistent with this, microglia, but not macrophages, from TLR4-/- animals express lower levels of MHCII under homeostatic conditions, prior to infection and lower total numbers of MHCII expressing microglia (and total microglia) during JHMV infection when compared to WT mice." (PMID 31309928, 2019). "Interestingly, direct infection of isolated alveolar macrophages with PR8 also shows an increase in TLR9, TLR7 and TLR3, with no changes in TLR2, and reduced TLR4." (PMID 30682165, 2019). "Interestingly, the expression of these tolerogenic DCs was observed following infection with live MAH, but not with inactivated MAH, and when TLR2 and TLR4 were co-involved." (PMID 31440223, 2019). "Expression of both TLR4 and TLR21, but not TLR2, is readily increased (6 h post infection) in cecal tissues in response to C. jejuni inoculation in 1-day-old birds, whereas in 2- and 4-week-old broiler chicks this is accompanied, however, by only a limited cytokine gene expression." (PMID 30234123, 2018). "In addition, L. major infection induces NOS2 expression by activating TLR4, although ARG1 expression is independent of TLR4 during infection in vivo and in vitro." (PMID 30555476, 2018). "We also speculated that TLR4 and C23 have no additional functions after RSV is internalized, as the expression levels of these two membrane receptors were decreased after 4 h of infection." (PMID 29427996, 2018).
infection (continued). "Blocking TLR2, but not TLR4, and inhibition of PI3K, reduced cytokine production to near background levels in primary BMM and the murine RAW264.7 macrophage cell line responding to infection with P. gingivalis." (PMID 28848717, 2017). "At later stages, all mice control infection and compensate for the lack of TLR2 and TLR4 by additional unknown mechanisms." (PMID 28119856, 2016). "Thus, by co-operating with CD14 in both R- and S-LPS loading onto TLR4/MD-2, CD36 can enhance the sensitivity of tissue-resident macrophages in detecting infections by Gram-negative bacteria." (PMID 27073833, 2016). "This study represents the first demonstration that prior infection with Type A F. tularensis subsp tularensis, not but F. novicida or F. tularensis subsp holarctica LVS, substantially alters the pulmonary transcriptional response to a TLR4 agonist." (PMID 26510639, 2015). "It was discovered that a unique complex of TLR4, MD2, and CD44 recognizes hyaluronan in noninfectious inflammation, which is different from the TLR4, MD2, and CD14 complex that recognizes LPS during infection." (PMID 23097717, 2012). "In addition, the experiments performed confirm previous findings concerning the lack of significant contribution of TLR4 and TLR2 with regard to spleen (and liver) infection, but reveal their significant contribution preventing lung infection." (PMID 22973560, 2012). "However, TLR4−/− and MyD88−/− mice, and also wild-type, TLR2−/− and TRIF−/− mice, were refractory to infection when exposed to C. difficile without any prior antibiotic treatment (data not shown)." (PMID 21738466, 2011). "TLR4 ligation, in the absence of treatment with specific agonists, did not contribute to worsened disease in MA15-infected BALB/c mice since infection of TLR4−/− BALB/c mice did not result in significant differences in clinical disease when compared to wild type BALB/c mice (data not shown)." (PMID 19851468, 2009). "Administration of poly(I:C) protected mice showing increased survival of mice even with a challenge infection with a 10-fold-higher HSV2 load.In contrast, treatment with TLR4 or TLR2 ligands does not lead to a protective effect against a challenge infection with intravaginal HSV2." (PMID 19088911, 2008). "Knockdown of TLR4 or SLAMF1 did not substantially alter HMPV-induced STAT1 phosphorylation at early time points, although SLAMF1 depletion significantly reduced STAT1 phosphorylation at 20 h post-infection, consistent with the reduced HMPV-N mRNA and protein levels in these MDMs." (PMID 41346628, 2025). "In addition, TLR4 activates NLRP3 inflammatory bodies through a non-classical pathway by recognizing extracellular LPS, which is pivotal in the host defense against pathogen infection and the regulation of inflammatory responses." (PMID 36838365, 2023). "Although TLR4 activation does not lead to DKK1 release from platelets,the finding that platelet TLR2 mediates the induction of DKK1 suggests that this mechanism may play a role in the initiation of infection and pathogenesis of other Leishmania species." (PMID 37885890, 2023). "However, dietary BLJ supplementation remarkably downregulated TLR-4 and TRAF-6 gene expression levels, decreased IL-1β gene expression levels and increased A20 and SOCS-6 mRNA levels in the jejunal mucosa of broilers regardless of NE infection." (PMID 32110391, 2020). "Following experimental infection with D. nodosus and vaccination no changes in TLR4 mRNA expression in peripheral blood leukocytes was observed; in contrast, TLR2 mRNA expression levels increased in peripheral blood in leukocytes response to both, infection or vaccination." (PMID 28338081, 2017). "We have previously shown that CD8+ T cells are involved in the control B. microti infection in vivo as well as in macrophages in vitro and, thus, defective control of infection observed in the absence of TLR2 and TLR4 could be related with a lower generation of B. microti-specific CD8+ Tc cells." (PMID 28119856, 2016).
infection (continued). "To that end, we stimulated different TLRs with their known ligands (e.g. TLR2 was stimulated with Pam3Csk4; TLR4 was stimulated with LPS, TLR7 was stimulated with imiquimod and TLR9 was stimulated with CpG-DNA) in the presence or absence of stimulation with Rv2463 or infection with M. tb H37Rv." (PMID 25915405, 2015). "Interestingly, whereas TLR4 inhibition (TAK-242, 10 μM) did not alter enhanced OAS1 and IRF7 expression in response to hypoxic priming and SARS-CoV-2 infection, it completely abolished the expression of chemokine ISGs CCL2 and CXCL10, despite the fact that the infection rate was not affected." (PMID 37377965, 2023). "Moreover, infection of human moDCs with H. pylori rapidly induces SOCS3 expression, which requires the type IV secretion system (T4SS), release of TNFα, and signaling via the MAP kinase p38, but appears to be independent of TLR2, TLR4, MEK1/2 and STAT proteins." (PMID 33023610, 2020). "As LPS is an active component of cigarette smoke, and down regulation of TLR4 expression by LPS in cigarette smoke, otherwise known as LPS tolerance, may result in impaired HBD2 production in response to Gram-negative pathogens, facilitating colonization and infection." (PMID 16219107, 2005).
cancer (962 papers, 2006 to 2026). A tumor composed of atypical neoplastic, often pleomorphic cells that invade other tissues. "The anti-cancer response of macrophages is triggered by the recognition of cancer cells, with TLRs, particularly TLR4, playing a key role by detecting danger-associated molecular patterns released by cancer cells." (PMID 41438574, 2026). "On the other hand, in line with the concepts reported in the previous section concerning TLRs, a positive association of TLR4 activation with CC worsening has been highlighted, whereas lower TLR4 levels were associated with reduced cancer growth." (PMID 40278303, 2025). "Previous studies have reported that TLR4 is overexpressed in ESCC, that its overexpression is associated with poor prognosis, and that it promotes cancer cell proliferation through the TLR4 signaling pathway." (PMID 41465449, 2025). "For instance, butyrate has been reported to downregulate TLR4 expression in intestinal epithelial cells, thereby reducing inflammation and potentially lowering cancer risk." (PMID 41386875, 2025). "Given the importance of chemotherapy in cancer treatment and the challenges it faces, this paper focuses on the TLR-4 activation mechanisms underlying chemotherapy-induced resistance in specific cancer types." (PMID 40404908, 2025). "Numerous single-nucleotide variants and mutations were identified in the TLR4 gene with strong association with several cancer types." (PMID 38606218, 2024). "This approach holds promise for enhancing the efficacy of cancer therapies by addressing specific molecular pathways associated with TLR4 and HPV infection." (PMID 38254888, 2024). "Further studies on larger sample sizes, different ethnic groups, exposures, and other factors would provide concrete evidence about the role of TLR4 gene variants in establishing a cancer phenotype." (PMID 38606218, 2024). "Single nucleotide polymorphisms (SNPs) on the TLR4 gene have been reported to increase or decrease susceptibility to various cancers in other organs." (PMID 39684439, 2024). "This suggests that the A allele enhances TLR4 transcriptional activity, potentially facilitating cancer progression." (PMID 39026223, 2024). "Previous studies have implicated TLR4 plays a key role in glucolipid metabolism, which is linked to the development of chronic inflammation and the progression of cancer." (PMID 38689341, 2024). "In ovarian cancer, TLR4-MyD88 signaling appears to be more active in high-grade cancer and is associated with reduced survival, increased recurrence, malignant transformation, and metastatic potential." (PMID 38785969, 2024). "They downregulate TLR4 and NF-κB, offering therapeutic benefits against cancer progression and metastasis-associated morphological changes." (PMID 38930793, 2024). "A similar kind of meta-analysis reported two SNPs of the TLR4 gene, viz., rs4986790 and rs4986791, to exhibit an increased risk of cancer with an odd’s ratio of 1.24." (PMID 38606218, 2024). "Various TLR4 SNPs have also been reported to influence susceptibility or protection depending on the cancer type." (PMID 39684439, 2024). "The inflammatory signaling pathway associated with LPS-activated TLR4/NF-κB is pivotal in promoting cancer invasion and metastasis in humans, contributing to the poor survival rate observed in CRC." (PMID 38612546, 2024). "Activation of TLR4, especially upon binding with lipopolysaccharide, has been linked to promoting the progression of BC by inducing gene expression associated with cancer progression." (PMID 38833016, 2024). "Studies has indicated that the effect of TLR4 SNPs on susceptibility to various cancer types is through the disruption of TLR4 signaling." (PMID 39026223, 2024). "TLR4 overexpression is associated with its immunosuppressive role in disease progression and increased cancer cell survival." (PMID 37822929, 2023). "Accumulated evidence has implicated TLR4 polymorphism in modulating the risk and development of various types of cancers." (PMID 37370894, 2023).